CCL22 (C-C motif chemokine ligand 22)
Diseases named in the same sentence as CCL22 in open-access papers (continued):
Sharing a sentence is not in itself a finding about the gene and the disease.
tumor (continued). "We observed a significant decrease in CCL22 mRNA expression in tumor tissue from runners, suggesting that decreased signaling by M2 macrophages or other stromal cells in the tumor microenvironment may result in a reduction in Treg recruitment." (PMID 24312199, 2013). "Expression of CCL22 was significantly associated with the infiltration of Tregs in the tumor bed (rs=0.282, P<0.0001), but not with those aggregates surrounding the tumor (rs=0.094, P=0.056)." (PMID 24124553, 2013). "Collectively, skewed immune cells such as TAM and Treg, special angiogenic vessels such as tumor-associated endothelial cells, and various proinflammatory cytokines/chemokines including CCL18 and CCL22 are synergistically involved in the suppression of anti-tumor immunity." (PMID 24213462, 2012). "This Treg recruitment may involve a CCR4-dependent trafficking induced by CCL22 released by tumor cells and immune cells infiltrating the tumors such as macrophages and DCs." (PMID 22110524, 2011). "Therefore, mast cells-induced IL-17 increased the level of CCL17 and CCL22 in tumor microenvironment, which then chemoattracted Treg cells to tumor." (PMID 20111717, 2010). "We found that BMMC injection increased the expression of CCL17 and CCL22 in tumor microenvironment, evaluated by real time RT-PCR, which could be blunted by IL-17 neutralization or blocking MDSC migration." (PMID 20111717, 2010). "Macrophages also produce CCL22, which promotes Treg recruitment to the tumor environment." (PMID 19641607, 2009). "Abundant accumulation of Tregs in tumor tissues might be due to the induction of CD4+CD25+ Tregs from peripheral CD4+CD25- T lymphocytes and/or migration of Tregs from other parts of the body to the tumor area by chemotactic factors like CCL22." (PMID 18294387, 2008). "Additionally, tumor-induced CCL22 production by eosinophils may facilitate the recruitment of regulatory T cells, further establishing a microenvironment favorable to tumor metastasis." (PMID 41401745, 2026). "Thus, the recruitment of Treg mediated by CCL22 is an important component of tumor immune escape." (PMID 39232378, 2024). "Accordingly, CCL22 remaining in tumor cells does not affect Treg invasion and may be associated with a better outcome." (PMID 39232378, 2024). "In an in situ PDAC mouse models, spMEXO could exert potential therapeutic effects by promoting the maturation of DCs, activation of CTLs, secretion of anti-tumor cytokines and blocking recruitment of Tregs by DCs through the CCR4/CCL22 axis, successfully inhibiting tumor growth." (PMID 38298192, 2024). "Specifically, tumor-associated macrophages (TAMs) and cancer-associated fibroblasts (CAFs) induce the upregulation of regulatory T cells (Tregs) through the release of interleukin-10 (IL-10), transforming growth factor-beta (TGF-β), and C-C motif chemokine ligand 22 (CCL22)." (PMID 39200233, 2024). "However, there is also some literature showing that CCL22 can promote tumor growth." (PMID 36969873, 2023). "We observed whether co‐inhibition of FAK and Gli1 could inhibit CCL22‐mediated tumor malignancy." (PMID 37846367, 2023). "Likewise, we identified CCL22 as the highest validated prognostic signature in 12 TCGA cancers (the highest bar); Moreover, we know it acts as a chemokine contributing to the modification of tumor microenvironment and resistance to the immune system." (PMID 35031021, 2022). "Therefore, it is pertinent to ask whether CCL22 might promote tumor progression via the inducement of M2a macrophage generation." (PMID 35805111, 2022). "Many studies have proved that TAMs could promote tumor progression by secreting CCL22." (PMID 35805111, 2022). "Significant decreases in the expression of cytokines are associated with tumor-associated macrophages (TAMs), including IL-4, IL-10 CCL-2, CCL-22, and CXCl-12, and suggest that the reduction in macrophages within the treated tumors could be indicative of a decrease in TAMs." (PMID 33956631, 2021).
tumor (continued). "Activated (M2) macrophages might be a critical factor to contribute to poor prognosis in HCC and induces tumor cell invasion through epithelial-to-mesenchymal transition (EMT) induced by CCL22, which implies that CCL22 is highly expressed both in tumor and stromal cells." (PMID 34948424, 2021). "Besides CAFs, tumor-associated macrophages (TAMs), as myeloid derived suppressor cells, contribute to an immunosuppressive microenvironment and support tumor growth as they are a source of immunosuppressive cytokines (e.g., CCL17, CCL18 and CCL22) and tumor promoting growth factors (VEGF-A, TNF-α)." (PMID 34064974, 2021). "M2-like TAMs block CD8 T cell-mediated anti-tumor immune response either directly, through their expression of inhibitor ligands, such as the programmed death-ligand 1 (PD-L1), or indirectly, via the C-C motif chemokine ligand 22 (CCL-22)-mediated recruitment of regulatory T cells (Tregs)." (PMID 34359785, 2021). "Chemokines involved in the recruitment of multiple immune cell subsets (Cxcr4, Cxcl13, Ccl22) were upregulated in parallel with the co-stimulatory molecules Icos and the checkpoint receptor Ctla4, suggesting complex immunological changes in the tumor microenvironment (TME) in response to treatment." (PMID 34445452, 2021). "Notably, TAMs also produce CCL17 and CCL22 to promote migration of CCR4+ Tregs to the tumor site." (PMID 32707850, 2020). "Additionally, tumor cells or tumor‐associated macrophages (TAMs) could also secrete CCL17 and CCL22 which are able to recruit CCR4+ regulatory T cells (Treg)." (PMID 31231980, 2019). "Hence, we speculated that the down-regulated expression of iNOS and CCL22 in macrophage after eosinophils depletion would hamper cryo-thermal-induced anti-tumour immunity." (PMID 31519961, 2019). "In addition, since TAMs produce the chemokine CCL22 to attract regulatory T cells and myeloid-derived suppressor cells to the tumor site, neutralization of CCL22 may reduce this potential adverse effect." (PMID 30062558, 2018). "In addition, it is well known that CCR4 is predominantly expressed by effector Treg cells, and Treg migration and infiltration into various tumor tissues are dependent on the expression of CCR4 ligands including CCL22 produced by tumor cells or infiltrating macrophages." (PMID 29383167, 2017). "This detrimental action of CCL22 may represent a tumor immune-escape response mechanism." (PMID 29099057, 2017). "Taken together, we reveal an interesting result that fucoidan can inhibit tumor cell migration and lymphocytes recruitment by suppressing CCL22 in M2 macrophages via NF-κB-dependent transcription, which may be a novel and promising mechanism for tumor immunotherapy." (PMID 27775051, 2016). "In addition, exploration on whether the Tregs recruited into the tumor bed by CCL22 and TGF-β1 are heterogeneous populations and may have different roles in tumor immunity would be another interesting study." (PMID 24124553, 2013). "Ccl13, Ccl18 (human only), Ccl22, and to a lesser extent Ccl17 are important chemoattractant for immune-inhibitory cells, such as Treg, which might inhibit antitumor immunity resulting in tumor growth and decreased patient survival." (PMID 23316105, 2012). "Interestingly in these patients CCL22 was not produced by the tumor, but released by the “bystanding”, tumor-associated macrophages (TAMs)." (PMID 24212779, 2011). "CCL22 has been linked to the recruitment of suppressor T cells, but it also recruits other immune cells which may reduce tumor growth in the absence of Tregs." (PMID 22013484, 2011). "(c) Signaling molecules also play a role, as the density of tumor-infiltrating T cells is negatively associated with expression of VEGF, B7-H1/PD-L1 and endothelin B receptor by tumors and positively associated with expression of the chemokines CXCL9, CCL21, CCL22, CCL2 and CCL5." (PMID 19641607, 2009).
tumor (continued). "Recruitment is driven mainly by CCL20-CCR6 and CCL22/CCL17-CCR4 signaling, while CCR8 marks highly suppressive tumor-resident Tregs." (PMID 42196608, 2026). "Furthermore, CTCL cells themselves secrete immunomodulatory chemokines such as CCL5 and CCL22, which attract regulatory T cells and M2-polarized macrophages, fostering a highly immunosuppressive microenvironment that promotes immune evasion and sustained tumor progression." (PMID 41614909, 2026). "Our analysis revealed that CCL22 was expressed at low levels across all cell types, whereas TNFSF10 exhibited higher expression in cancer cells compared with other cell types in the tumor microenvironment." (PMID 41295982, 2026). "The transcriptional biomarker score we developed is based on the expression of two immune-related genes, CCL22 and TNFSF10, each playing distinct roles in immune regulation and tumor biology." (PMID 41295982, 2026). "Tumor cells, along with other stromal and immune cells in the TME, secrete chemokines including CCL22, CCL20, and CXCL12, which bind to CCR4, CCR6, and CXCR4 on Tregs and direct their recruitment and activation within the TME." (PMID 41890756, 2026). "In TCGA-BRCA and TCGA-PRAD patient datasets, both CCL22 and TNFSF10 expression were positively correlated with tumor infiltration of some immune cell types." (PMID 41295982, 2026). "In M0 macrophages, 4OI downregulated the monocyte and T-cell chemoattractant CCL22 and anti-inflammatory marker CD206, and exerted tumor promoting effects by directly downregulating PPARG." (PMID 40552282, 2025). "Updating evidences suggest a more complicated function of tumor‐derived chemokines, such as CCL22 and CXCL12 in orchestrating tumor immune evasion." (PMID 41427020, 2025). "This expansion is orchestrated by the tumor microenvironment, where immunosuppressive cytokines such as TGF-β and IL-10 induce naïve T cell conversion into Tregs, and chemokines like CCL22 mediate recruitment via CCR4 signaling." (PMID 41181112, 2025). "They secrete anti-inflammatory cytokines, including IL-10, TGF-β, CCL22, and CCL17, which support immune suppression and aid in tumor progression." (PMID 40867316, 2025). "CCL22 plays a key role in attracting Tregs to the TME, leading to an immunosuppressive environment that favors tumor growth." (PMID 40739089, 2025). "CCL17 and CCL22 promote the homing of Tregs to the lungs, whereas CCL2 is required for the recruitment of Tregs to tumor sites." (PMID 39740041, 2025). "CCL22 and CCL5 are key chemokines within the tumor TME that participate in immune evasion by recruiting immunosuppressive cells." (PMID 40739089, 2025). "Tregs accumulate in the TME in response to chemokines such as CCL22, CCL17, and CXCL12, which are secreted by both tumor cells and stromal components, including CAFs." (PMID 40507214, 2025). "M2 expresses high levels of CD163, CD206, CCL18, and CCL22, releasing anti-inflammatory (TGF-β, IL-4, and IL-13) and inflammatory (IL-6, IL-12, and TNF-α) factors, as well as tumor-promoting arginase-1 and VEGF, modulated by TME signals." (PMID 40940877, 2025). "In epithelial ovarian cancer, for example, the chemokine CCL22 recruits CD4+CD25+FOXP3+ cells, leading to suppression of antitumor immunity and favoring tumor progression." (PMID 41394821, 2025). "TAMs interact intensively with tumor and lymphoid cells, expressing high levels of CCL2, CCL18, and CCL22 to recruit suppressive Tregs, while PD-L1 and IDO1 expression directly inhibits T cells effector function." (PMID 41562080, 2025). "HRS cells secrete the chemokines CCL17 (also known as thymus and activation-regulated chemokine, TARC) and CCL22, which recruit CCR4-expressing Th2 cells and Tregs, promoting an immunosuppressive milieu that facilitates tumor survival." (PMID 40806636, 2025). "CCL22 is a chemokine that recruits CCR4-expressing cells, particularly Treg, to sites of inflammation or immune regulation, such as tumor microenvironments." (PMID 40894040, 2025).
tumor (continued). "Mechanistically, CD68+ CAFs appear to enhance anti-tumor immune responses by promoting the secretion of CCL17 and CCL22, which facilitate regulatory T cell recruitment in a potentially regulatory feedback context." (PMID 41583435, 2025). "In clinical trials, inhibitory therapeutic targeting of the CCL2 and CCL22 axes were often unfavorable for patients, reinforcing an overall anti-tumorigenic effect of CCL2 and CCL22 at least in certain tumor settings." (PMID 40595293, 2025). "Mechanistically, L1CAM upregulates CCL22 expression through the activation of the PI3K/Akt/NF-κB signaling pathway, facilitating Treg recruitment to the tumor site." (PMID 40134607, 2025). "Abnormal tumor vessels further exacerbate hypoxia, which in turn increases the secretion of chemotactic cytokines - including CCL2, CCL22, CCL28, CXCL8, and CXCL12 - that recruit immunosuppressive MDSCs, M2-like TAMs, and Tregs into the tumor." (PMID 41019982, 2025). "Experiments with recombinant CCL22 and neutralizing antibodies have demonstrated significant alterations in the expression of EMT markers and tumor cell invasion." (PMID 39286635, 2024). "Chemokines secreted by macrophages, like CCL17 and CCL22, attract Tregs to the tumor area, enhancing Treg infiltration within the TME and further sustaining the tumor’s ability to evade immune detection." (PMID 39290699, 2024). "CCL22 is a ligand of CCR4, that is preferentially expressed on regulatory T-cells (Treg) and mediates Treg migration into the tumor tissue via chemokine gradient formation." (PMID 39232378, 2024). "C-C motif chemokine ligand 22 (CCL22), also known as macrophage-derived chemokine (MDC), is produced by certain tumor cells but also immune cells." (PMID 38928238, 2024). "CCL22 also plays a crucial role in CRC chemoresistance by activating the PI3K/Akt pathway, thereby reducing the effectiveness of 5-fluorouracil in curbing tumor growth." (PMID 39286635, 2024). "Meanwhile, macrophages can promote tumor invasion and metastasis through secretion of various cytokines (e.g., TGF-β, IL-10, arginase 1) and chemokines (e.g., CCL5, CCL17, CCL18, CCL22)." (PMID 38637499, 2024). "The decrease in the percentage of M2 TAMs visible by cytometry was also confirmed by the decrease in CCL17 and CCL22 mRNA (M2 macrophages markers), as well as CXCR2 mRNA in the tumor." (PMID 38504270, 2024). "CyTOF analysis showed that compared with the Ki67− counterparts, Ki67+ Tregs expressed higher levels of CCR4 and CCR5, receptors for the chemotactic factors CCL22 and CCL5 that are mainly produced by tumor cells, macrophages and DCs in the TME." (PMID 39438442, 2024). "Pro-inflammatory TAMs express TH1 response-inducing cytokines such as IL1α, IL1β, IL12 and TNFα while pro-tumor TAMs express IL10, CCL8, and CCL22 that are tumor promoting." (PMID 38802355, 2024). "PBMCs were also identified as the main producer of CCL22 in the SN in the context of coculture, based on the finding that PBMC incubation with cell-free tumor SN induced a significant upregulation of secreted CCL22." (PMID 39232378, 2024). "The expression of DNMT3A increased significantly when EZH2 was knocked down; CCL22 and CCR4 were downregulated in tumor tissues, and EMT-related protein expression also changed consistent with in vitro results." (PMID 39513112, 2024). "This activation leads to increased tumor cell migration and invasion, which can be mitigated by pharmacological inhibition of FAK or by employing anti-CCL22 treatments." (PMID 39286635, 2024). "The activation of TLR4 on macrophages increases the production of IL-10 and C-C Motif Chemokine Ligand 22 (CCL22) that promote the expansion and activation of CD4+CD25highFOXP3+ Tregs, suppressing immune responses against the tumor." (PMID 37345131, 2023). "Some information shows that TAM can not only promote angiogenesis and support tumor growth by secreting cytokines such as TGF-β, but also recruit T cells by secreting CCL17 and CCL22." (PMID 36969873, 2023).
tumor (continued). "In summary, our results showed that the combination of pexidartinib and PD-1 antibody showed a synergy and significantly improved the anti-tumor efficacy, through pexidartinib increasing CD8T/Treg ratio by reducing TAM-derived CCL22." (PMID 36969873, 2023). "In addition, CITE-seq analysis also showed an increase in CCL22 expression in CD81+migcDC1s upon Flt3L treatment and could together with the CCL22 expression observed in migDCs be the cause of the increased CCL22 observed in the E0771 tumor supernatants." (PMID 37622122, 2023). "Several chemokine ligands are expressed by the tumor: CCL17 and CCL22 promote recruitment of CCR4+ Tregs, while CXCR3—along with its ligands, CXCL9 and CXCL10—drives cytotoxic lymphocyte trafficking into the GBM tumor site." (PMID 37443804, 2023). "The results showed that the Ccl22 transcription level of CD45− cells and macrophages increased gradually with the time of tumor progression, while the Ccl22 mRNA of T cells remained at a low level." (PMID 36969873, 2023). "The results of RT-qPCR showed that the expression levels of CCL2, CCL22, TNF-α and IFN-γ in tumor tissues were significantly increased after TCS treatment." (PMID 36674931, 2023). "In our study, CCL22 level was significantly inhibited when treated with PLX3397, which further inhibited Treg infiltration in the tumor environment, which improve the anti-tumor effect of PD-1 antibody therapy methods." (PMID 36969873, 2023). "According to our results, TAMs‐released CCL22 stimulates the CCR4/FAK/AKT/Gli1 signaling in ESCC cells, providing a novel TAMs/intratumoral axis in tumor progression." (PMID 37846367, 2023). "In the tumor microenvironment (TME), tumor cells produce chemokine CCL22 to mediate the entry of regulatory T cells (Tregs) into the TME." (PMID 37398678, 2023). "Expression of chemokine receptors that match ligands secreted by the tumor such as CCL2, CCL22, CXCL16, CX3CL1, CXCL1 and CXCL8 can enable CD8+ T cells to enter the tumor." (PMID 37301772, 2023). "Binding of CCL22 with CCR4 enhances T-cell dendritic cell binding and increases CTL activation, while enhancing tumor cell responses to IFN-γ." (PMID 36674931, 2023). "Both CCL22 and CCL23 were immunosuppressive chemokines derived from macrophages, which had a unique role in inhibiting anti-tumor immunity." (PMID 38075694, 2023). "The results of tumor tissue samples showed that the protein levels of chemokines CCL2 and CCL22, as well as TNF-α and IFN-γ, were significantly increased upon TCS treatment." (PMID 36674931, 2023). "Mechanistically, TAM-secreted C-C motif chemokine ligand 17 (CCL17) and CCL22, via membrane receptor CCR4, activated the PI3K/AKT pathway in CRC tumor cells." (PMID 37658050, 2023). "There are several reports which show that blocking the CCL22/CCL17–CCR4 axis by using specific antibodies, antagonists or siRNA, resulted in remarkable reduction in Tregs and increased anti-tumor responses." (PMID 37122749, 2023). "In order to make it clear that CCL22 was involved in Treg infiltration during treatment, we analysis the CCR4 level in tumor infiltrated Treg, a relatively high CCR4 level was observed in Treg, we conducted a compensation experiment." (PMID 36969873, 2023). "The TAMs are primarily present in the tumor stroma, and POSTN encourages CD163+ macrophages to release various cytokines, including Treg-related chemokines (CCL17 and CCL22)." (PMID 37525217, 2023). "Treg cells are mainly recruited to the tumor microenvironment by chemokines such as CCL1, CCL17, CCL22, CCL28, CXCL9, CXCL10, and CXCL11." (PMID 37686093, 2023). "M2 macrophages release epidermal growth factor, chemokines (such as CCL24and CCL22), and cytokines (such as TNF-α and IL-6) that directly promote tumor growth and metastasis and promote tumor progression." (PMID 37153586, 2023). "CCL22 is secreted by PAAD cells, and chemotactic Tregs accumulate to the tumor site by binding the CCR4 receptor of Tregs." (PMID 36782176, 2023).